PLCG1 (phospholipase C gamma 1)
Diseases named in the same sentence as PLCG1 in open-access papers (continued):
Sharing a sentence is not in itself a finding about the gene and the disease.
glioma (15 papers, 2012 to 2025). A benign or malignant brain and spinal cord tumor that arises from glial cells (astrocytes, oligodendrocytes, ependymal cells). "PLCG1 overexpression is associated with tumor growth and poor survival in gliomas in adult patients." (PMID 35677632, 2022). "PLCγ1 activation is linked to increased invasion of gliomas making PLCγ1 a likely candidate linking the cell surface receptor (activated by microglia) to the Pyk2 pathway." (PMID 26098895, 2015). "Furthermore, the cancer genome atlas (TCGA) and the Chinese glioma genome atlas (CGGA) databases verified that elevated PLCG1 expression was associated with tumor progression and poor survival in LGG patients." (PMID 34697421, 2022). "The hypothesis that PLCγ1 could work as a potential therapeutic target for gliomas is also supported by a recent work that claims an association between PLCγ1 overexpression, tumor progression, and negative prognosis in patients characterized by IDH-wildtype lower-grade gliomas (LGGs)." (PMID 37238668, 2023). "Functional inhibition of PLCγ1 reduces glioma growth and migration, and TrkB-dependent PLCγ1 and Ras/ERK activation support resistance to apoptosis." (PMID 41511337, 2025). "TCGA glioma cohort analysis and RT-qPCR results showed that PLCG1 transcription was significantly decreased, while NOD2 transcription was elevated in patients with GBM compared with patients with LGG." (PMID 40761791, 2025). "FGFR1 signaling promotes radioresistance in glioma cell lines through PLC1γ (Phospholipase C Gamma 1) and HIF1α pathways." (PMID 38255923, 2024). "FGFR1 signaling also promotes radioresistance in glioma cell lines through PLCγ1 and hypoxia-inducible factor 1-alpha (HIF1α)." (PMID 38255923, 2024). "Consistent with our results, a high expression of PLCG1 predicts poor survival in adult lower-grade gliomas." (PMID 35741587, 2022). "The mRNA expression levels of phospholipase Cγ1 (PLCG1) are much higher in IDH wild-type (IDHwt) lower-grade gliomas (LGGs) than in that of IDH mutant (IDHmut) LGGs." (PMID 34697421, 2022). "A recent study has shown that PLCγ1 is a target of PTPRM and dephosphorylation of PLCγ1 is a major pathway by which PTPRM suppresses glioma cell migration." (PMID 23185569, 2012). "While PLCγ1 normally participates in neuronal and astrocytic plasticity, gliomas co-opt this signalling architecture to promote proliferation, motility, and survival, and elevated PLCG1 expression correlates with aggressive disease in multiple transcriptomic analyses." (PMID 41511337, 2025). "Recent reports have shown that a reduction in expression of Protein Tyrosine Phosphatase-1B (PTP1B) and T-Cell Protein Tyrosine phosphatase (TC-PTP) reduced ERK phosphorylation in MCF-7 cells, and PTPRM suppressed glioma cell migration by dephosphorylation of PLCγ1." (PMID 23185569, 2012). "Indeed, past studies have shown a link between PLCγ1 inhibition and the arrest of glioma cell motility of fetal rat brain aggregates and the reduction of cell invasion abilities following its downregulation, suggesting a possible anti-invasive therapeutic strategy for glioblastoma." (PMID 37238668, 2023). "In glioma cells, apoptosis and autophagy are integrated into a stress-responsive regulatory network defined by oncogenic PI3K/Akt/mTOR, Ras/Raf/MEK/ERK, and PLCγ1/PKC signalling." (PMID 41511337, 2025). "PLCG1, a member of the phospholipase C (PLC) family of enzymes, is involved in the development of glioma through the activation of growth factors such as EGFR and PDGFR." (PMID 38025749, 2023). "Our results using antibody microarrays suggest that factors released from microglia upregulate PLCγ1 and EGFR protein levels in C6 glioma cells." (PMID 26098895, 2015).
glioma (continued). "All these together indicate that PLCγ1 and EGFR might be involved in enhancing migration of glioma cells exposed to microglia and could potentially be acting as upstream regulators of the Pyk2 pathway." (PMID 26098895, 2015). "Although direct glioma-specific evidence linking PLCγ1/PKC-mediated phosphorylation to disruption of the Bcl-2:beclin-1 complex is limited, existing studies demonstrate that PLCγ1-driven Ca2+ flux modulates autophagy-apoptosis balance by influencing beclin-1 availability at the ER membrane." (PMID 41511337, 2025).
gastric cancer (12 papers, 2008 to 2026). A primary or metastatic malignant neoplasm involving the stomach. "BPTF has been shown to contribute to erlotinib resistance in gastric cancer by regulating the c-MYC/PLCG1/p-Erk axis." (PMID 41602481, 2026). "We investigated that PLCG1, CASP5, CASP8 and NLRP3 displayed the highest mutation frequencies in gastric cancer specimens." (PMID 37595258, 2023). "BPTF inhibitor increases gastric cancer response to Erlotinib by epigenetically regulating c‐MYC/PLCG1/pErk axis." (PMID 37863665, 2023). "To further investigate the role of PLCγ1 in gastric cancer cell proliferation, we treated gastric cancer cells with a PLCγ1 inhibitor, U73122, to observe if it will affect gastric cancer cell viability." (PMID 28061477, 2017). "Inhibition of PLCγ1 prevents H. pylori induced cell scattering, providing a possible intervention strategy against invasive gastric cancer." (PMID 18194572, 2008). "Our findings indicate that ASTX can suppress H. pylori-induced gastric cancer progression by inhibiting cytoskeleton reorganization and reducing cell motility through downregulation of c-MET, EGFR, PI3KC2, PLCγ1, Cdc42, and ROCK1." (PMID 32679742, 2020). "In conclusion, ASTX can suppress H. pylori-induced gastric cancer progression by inhibiting cytoskeleton reorganization and reducing cell motility through downregulation of c-MET, EGFR, PI3KC2, PLCγ1, Cdc42, and ROCK1." (PMID 32679742, 2020). "In gastric cancer cells, VEGFR2 transfers signals through the activation of PLCG1 and MAPK1/3 pathways." (PMID 31570733, 2019). "To confirm this in gastric cancer cells, we used inhibitor of signal transduction component to identify the participation of MAPK/ERK and PLCγ1-mediated pathways in the process." (PMID 23613900, 2013).
T-cell lymphomas (10 papers, 2017 to 2025). "PLCG1 mutations were also discovered in T-cell lymphomas, including cutaneous and adult T-cell leukemia/lymphoma." (PMID 37371495, 2023). "Mutations in the TCR signaling components and PLCG1 have been observed in T-cell lymphoma patients, and these mutations are associated with poorer overall and progression-free survival rates based on several clinical studies." (PMID 37371495, 2023). "Phospholipase C gamma-1 (PLCG1) gene has been found associated with noteworthy T-cell lymphomas like peripheral T-cell lymphoma (PTCL), angioimmunoblastic T-cell lymphoma (AITL), cutaneous T-cell lymphoma (CTCL) and adult T-cell leukemia/lymphoma." (PMID 34793541, 2021). "The PLCγ1 R48W mutation frequently found in T-cell lymphoma affects the nPH domain, implicated in inositol-lipid binding, and provides a possible candidate for this mechanism." (PMID 31918402, 2020). "Recently, two hot-spot PLCG1 mutations (encoding p.Ser345Phe and p.Ser520Phe) that enhance PLCƔ activity have been reported in T-cell lymphoma." (PMID 28505169, 2017). "We therefore hypothesized that rs3795128 was linked to T-cell lymphomas through its strong LD with the missense mutation in PLCG1." (PMID 31681408, 2019). "Using the T cell lymphoma line Hut78 as a model, we found that PLCG1 mutants induced cell aggregation by enhancing ICAM-1 expression." (PMID 40796680, 2025). "PLCG1 mutations have also been detected in other mature T-cell malignancies, notably HTLV-1 associated ATLL, PTCL(NOS), hepato-splenic T-cell lymphomas and AITL with the PLCG1 p.S345F and R48W variants being two of the most frequently reported." (PMID 36505788, 2022). "The mechanism of action of PCI-34051 was demonstrated to involve phospholipase C gamma 1 (PLCγ1) activation, which is a signal transducer following T cell receptor activation, and calcium-induced apoptosis in T cell lymphomas." (PMID 35897717, 2022). "PLCG1 gene is responsible for many T-cell lymphoma subtypes, including peripheral T-cell lymphoma (PTCL), angioimmunoblastic T-cell lymphoma (AITL), cutaneous T-cell lymphoma (CTCL), adult T-cell leukemia/lymphoma along with other diseases." (PMID 34793541, 2021). "For T-cell lymphoma six genes are found in cosmic (JAK1, PLCG1, FYN, ARID1A, EP300, and MAP3K1), and 13 are known oncogenes." (PMID 34570764, 2021).
epilepsy (9 papers, 2015 to 2025). A brain disorder characterized by episodes of abnormally increased neuronal discharge resulting in transient episodes of sensory or motor neurological dysfunction, or psychic dysfunction. "PLCG1, an intracellular protein highly expressed in brain tissue, is linked to MS and other neurological disorders like Alzheimer’s, Huntington’s, and epilepsy." (PMID 40026247, 2025). "This is in accordance with the results showing a rapid upregulation in BDNF under the same conditions, and with the effect of a peptide that uncouples TrkB from PLCγ1 which prevents epilepsy induced by status epilepticus after kainate infusion in the amygdala." (PMID 40890771, 2025). "Uncoupling of the BDNF receptor TrkB from PLCγ1 prevented epilepsy, suggesting that the effects of PLCγ1 on epilepsy depend on the specific neuronal population involved." (PMID 37371495, 2023). "PLCG1 has been proposed as a mediating factor in schizophrenia, bipolar disorder, Alzheimer’s, Huntington’s, and epilepsy." (PMID 35887162, 2022). "PLCβ1 knockout mice are afflicted with epilepsy while abnormal activity and expression level of PLCγ1 are detected in pathologies including Huntington's disease, depression and Alzheimer's disease." (PMID 25875657, 2015).
hepatocellular carcinoma (8 papers, 2017 to 2022). A malignant tumor that arises from hepatocytes. "Our previous studies indicated that phosphoinositide specific phospholipase Cγ1 (PLCγ1) was involved in autophagy induction in colon and hepatic carcinoma cells." (PMID 32210730, 2020). "It has been demonstrated that autocrine VEGF signaling promotes cell proliferation through a Phosphoinositide phospholipase C γ1 (PLCγ1) -dependent pathway in hepatocellular carcinoma cells and neoplastic Barrett's epithelial cells." (PMID 28061477, 2017). "The expression of PLCG1 also promoted hepatoma cell carcinogenesis in vitro and in vivo." (PMID 32508884, 2020). "Hence, we investigated the role of PLCγ1 in autophagy in human colon cancer and hepatocellular carcinoma." (PMID 29066806, 2017). "Consequently, these findings provide novel insight into autophagy regulation by PLCγ1 in colon cancer and hepatocellular carcinoma cells." (PMID 29066806, 2017). "Here, we investigated the relationship between PLCγ1 and autophagy in the human colon cancer cell line HCT116 and hepatocellular carcinoma cell line HepG2." (PMID 29066806, 2017). "Hence, these results support the notion that PLCγ1 inhibitor U73122 enhanced autophagy to promote ECM synthesis, consistent with our previous study in colon and hepatic carcinoma cells." (PMID 33372388, 2021). "To choose appropriate cell lines for subsequent experiments, we first detected the protein expression levels of PLCγ1 and LC3B (autophagy marker) via western blotting analysis in the colon cancer cell lines HCT116 and HCT8 and hepatocellular carcinoma cell lines HepG2 and Huh7." (PMID 29066806, 2017). "In this study, after detecting the expression levels of PLCγ1 and the autophagy marker LC3B in different colon cancer and hepatocellular carcinoma cell lines, we chose the colon cancer cell line HCT116 and hepatocellular carcinoma cell line HepG2 for subsequent experiments." (PMID 29066806, 2017). "Similarly, in the hepatocellular carcinoma cell lines, we observed higher PLCγ1 expression along with lower LC3B-II expression in HepG2 cells and lower PLCγ1 expression with higher LC3B-II expression in Huh7 cells." (PMID 29066806, 2017).
lymphoma (7 papers, 2019 to 2025). A malignant (clonal) proliferation of B- lymphocytes or T- lymphocytes which involves the lymph nodes, bone marrow and/or extranodal sites. "Phospholipase C gamma 1 (PLCG1) has been identified as the most frequently mutated gene in adult T-cell leukemia/lymphoma, suggesting a critical function of PLCG1 in driving T cell activation." (PMID 40796680, 2025). "PLCG1 is the most commonly mutated gene in adult T-cell leukaemia/lymphoma, accounting for approximately 40% of all cases." (PMID 37371495, 2023). "Together, our work reveals how hyperactive PLCG1 affects T cell signaling and drug resistance and uncovers insights on the pathogenesis mechanism of T-cell leukemia and lymphoma." (PMID 40796680, 2025). "To determine how PLCG1 mutants affect signaling in the context of T-cell leukemia and lymphoma, we used Hut78, a human T lymphoma cell line, as a model." (PMID 40796680, 2025). "Activating mutations of PLCG1 increasing the transcriptional activity of NF-κB via induction of MALT1 protease activity were also found in angioimmunoblastic T-cell lymphoma and other lymphomas derived from follicular T-helper cells." (PMID 30718475, 2019). "In addition to frequent somatic mutations in RHOA and epigenetic modifiers, several studies have shown frequent alterations affecting TCR signaling-related genes, including CD28, FYN, PLCγ1 and VAV1 in cutaneous T-cell lymphomas, AITL and adult T cell leukemia/lymphoma." (PMID 30814910, 2019).
Anxiety (6 papers, 2019 to 2024). Intense feelings of nervousness, tension, or panic often arise in response to interpersonal stresses. "Deficiency of Plcg1 in the forebrain resulted in hyperactivity, decreased anxiety, and depressive-like behavior." (PMID 39628496, 2024). "Our study found that SPS increased Plcg1 expression in PL-susceptible animals, which could heighten anxiety and depressive-like behavior following traumatic stress." (PMID 39628496, 2024). "Polymorphism in PLCγ1 was frequently found in bipolar patients and excitatory neuron-specific PLCγ1 knockout mice exhibited manic-like behaviors such as hyperlocomotion, decreased anxiety, increased hedonic action, and impaired learning and memory performance." (PMID 33808762, 2021). "Thus, the defects in the hippocampus and other brain regions rendered by GABAergic neuron-specific loss of PLCγ1 may account for the alterations in anxiety level and contextual fear memory." (PMID 31780806, 2019). "Plcg1 (phospholipase C, gamma 1) is involved in the regulation of anxiety and depressive-like behavior in animals." (PMID 39628496, 2024). "Mice with GABAergic neuron-specific deletion of PLCG1 showed handling-induced recurrent seizures with a reduced number of GABAergic synapses, decreased hippocampal inhibitory synaptic transmission, anxiety alleviation and fear memory disorder." (PMID 36920176, 2023). "Genetic deletions of PLCG1 in mice exhibited behavioral alterations, including hypoactivity and reduced anxiety." (PMID 33834688, 2021). "Literature mining-based network analysis identified Plcg1 as a hub in the constructed network, linking this gene to anxiety, depression, stress, the nervous system, and fertility, with 2 mined sentences identified linking this gene to anxiety-a medium confidence result." (PMID 36364936, 2022).
colorectal cancer (6 papers, 2015 to 2023). A primary or metastatic malignant neoplasm that affects the colon or rectum. "Colorectal cancer is linked to inflammation and phospholipase Cγ1 (PLCγ1) is associated with tumorigenesis and the development of colorectal cancer; however, evidence of mechanisms connecting them remains unclear." (PMID 29464031, 2018). "A previous study revealed that epidermal growth factor (EGF) stimulation activated NF-κB via PLCγ1 in colorectal cancer cells." (PMID 37408216, 2023). "PLCγ1 is ubiquitously expressed in mammalian cells, and has been reported to be highly expressed in some tumor tissues, including colorectal cancer, squamous cell carcinoma, and breast cancer, regulating cancer cell metabolism." (PMID 26633375, 2015). "As an example, elevated content of PLCγ1 in colorectal cancer tissues is observed." (PMID 26633375, 2015).
glioblastoma (6 papers, 2011 to 2023). The most malignant astrocytic tumor (WHO grade IV). "In particular, it was demonstrated that PLCγ1 gene expression was higher in glioblastoma patients’ tissue samples compared to in healthy controls and that PLCγ1 downregulation in in vitro models led to a reduction in cell migration and invasion abilities." (PMID 37238668, 2023). "On the other hand, a translational study conducted by the same research team identified and confirmed PLCγ1 as a key enzyme for glioblastoma progression." (PMID 37238668, 2023). "For instance, our recent publication reported the potential involvement of a specific PLC isoform, the PLCγ1, in the aggressiveness of glioblastoma." (PMID 35303162, 2022). "EGFR is an activator of PLCγ1 and EGFR gene amplification is one of the most frequent alterations occurring in glioblastoma and associated with profuse tumor cell invasion." (PMID 26098895, 2015).
ovarian cancer (6 papers, 2019 to 2023). A primary or metastatic malignant neoplasm involving the ovary. "Aberrant expression and regulation of PLCG1 have been linked to the development of various cancers, including breast, lung, pancreatic, gastric, prostate, and ovarian cancers." (PMID 36386841, 2022). "Through miRNA, these lncRNAs are connected with PRGs such as IRF1, NOD1, GSDMC, NLRP1, PLCG1, GSDME and GZMB to construct a pyroptosis related ceRNA regulatory network in ovarian cancer." (PMID 37859811, 2023). "provided a novel gene signature including 7 PRGs (AIM2, PLCG1, ELANE, PJVK, CASP3, CASP6, and GSDMA) for predicting the prognosis of ovarian cancer (OC) patients and laid a foundation for further studies of the relationships between PRGs and immunity in OC." (PMID 35912258, 2022). "In ERα-positive breast and ovary cancer cells, 17β-oestradiol induces rapid anticipatory activation of the UPR that is strictly PLCγ1 dependent." (PMID 31362705, 2019).